CD44 (CD44 molecule (IN blood group))
Diseases named in the same sentence as CD44 in open-access papers (continued):
Sharing a sentence is not in itself a finding about the gene and the disease.
neuroblastoma (continued). "Moreover, our results demonstrated an up-regulation of ALDH1A3 and downregulation of CD44 proteins upon glutamine starvation in MYCN-amplified neuroblastoma cells, while a downregulation of both CSC markers was observed in SH-SY5Y cells." (PMID 32483461, 2020). "CD44 utilization was not evaluated because of its association with good prognosis in neuroblastoma patients." (PMID 29156825, 2017). "By contrast, in neuroblastomas, CD44 expression is often low in advanced tumours." (PMID 25999819, 2015). "Furthermore, interaction of HA with CD44 on neuroblastoma cells and astrocytes induces their migration in vitro." (PMID 23468987, 2013). "Absence of functional CD44 hyaluronan receptor on human N-Myc-amplified neuroblastoma cells predicts risk of disease progression and dissemination." (PMID 21876694, 2012). "In addition, CD44 expression enhances filopodia growth of neuroblastoma cells." (PMID 28287145, 2017). "In another study, human neuroblastoma cell lines were injected subcutaneously into SCID mice, and their growth behavior and nestin as well as CD44 expression were analyzed." (PMID 34943921, 2021). "Over again, HCMV-IE and late proteins were expressed in 100% and 92% of primary neuroblastoma samples respectively; notably, HCMV proteins were detected in CD133 and CD44-positive neuroblastoma cells." (PMID 34566995, 2021). "We tested the viability after 24 h of treatment with bare or HA-capped AuNPs of CD44-positive cells (normal endothelial, HUVEC and prostate tumor, PC-3), in comparison with CD44-negative cells (neuroblastoma, SH-SY5Y)." (PMID 32349323, 2020). "Further, flow cytometric measurement determined the level of PSGL-1 in neuroblastoma cell lines to be more modest in comparison with CD24 and CD44." (PMID 29156825, 2017). "In neuroblastoma CD24 is highly expressed in undifferentiated tumors and the expression of CD44 is correlated with better prognosis." (PMID 29156825, 2017). "By treating the human neuroblastoma SH-SY5Y cells with all-trans RA, we observed a significant increase in the number of CD44+/CD49d+ cells, predominantly via the enhancement of CD49d expression." (PMID 26980066, 2016). "Among the favorable neuroblastoma genes examined (EPHB6, EFNB2, EFNB3, TrkA, CD44, MIZ-1), S(+)-ibuprofen augmented the expression of EPHB6 significantly in four of five neuroblastoma cell lines tested." (PMID 24173829, 2014). "In neuroblastomas, methylation of several genes, including MGMT, SLIT2, CD44, FLIP and RASSF1A, has been described." (PMID 17064406, 2006). "Genes involved in neuroblastoma, such as MYCN or CD44, are among them." (PMID 36675105, 2023). "In addition, IE and late-HCMV proteins are detected in 100% and 92% of primary neuroblastoma samples, respectively, including neuroblastoma cells, which express high levels of stemness markers such as CD133 and CD44." (PMID 35458542, 2022). "Of note, for the CD44-negative neuroblastoma, the aggregate distribution is quite similar in the cells incubated with bare AuNPs or with HA-capped NPs." (PMID 32349323, 2020). "Flow cytometry and Western blot experiments demonstrated high levels of CD44v6 expression in PC-3 cells and that CD44 is not expressed or is expressed at greatly reduced levels in human neuroblastoma lines." (PMID 32349323, 2020). "Y79 retinoblastoma cells and CD44-negative SK-N-DZ neuroblastoma cells transduced with adenoviral vectors in the presence of versican respond with an activation of transgene expression." (PMID 28684419, 2017). "SK-N-DZ neuroblastoma cells that are CD44-negative and do not bind HA were used to isolate the mechanisms being investigated to HA-CD44 independent steps." (PMID 28684419, 2017). "TrkA and CD44 co-expression has been already reported in neuroblastoma cells but the authors did not examine their interaction nor the resulting intracellular signaling." (PMID 25840418, 2015).
neuroblastoma (continued). "In addition, S(+)-ibuprofen enhanced the expression of some favorable neuroblastoma genes (EPHB6, CD44) and genes involved in growth suppression and differentiation (EGR1, EPHA2, NRG1 and SEL1L)." (PMID 24173829, 2014). "N-Myc-amplified neuroblastoma cell lines either do not express CD44 or express a non-functional receptor." (PMID 21876694, 2012). "Finally, the highest toxicity was detected in CD44-negative neuroblastoma cells, with a decrease of viability of ~40% and ~60% for treatments with bare AuNP and HA-capped NPs, respectively." (PMID 32349323, 2020). "Since HAS2, CD44, and VEGF endogenous mRNA expression levels were very low in HRA cells although their expression levels were high in U373MG human astrocytoma cells and SH-SY5Y human neuroblastoma cells, it was impossible to evaluate the effect of 4-MU treatment (data not shown)." (PMID 25304388, 2014). "A number of factors that correlate with the response to treatment and outcome of patients with neuroblastoma have been identified, including patient age, stage, histology, MYCN amplification, DNA ploidy, 1p deletions, 17q gain, TRKA expression and CD44 cell-surface expression." (PMID 11953858, 2002). "A total of 108 tumours were classified as neuroblastoma or ganglioneuroblastoma; 74 expressed TRKA protein, which strongly correlated with low stage, absence of N-MYC amplification, age (<1 year), CD44 expression and favourable clinical outcome." (PMID 9099963, 1997).
Obesity (45 papers, 2011 to 2026). Accumulation of substantial excess body fat. "Although a recent study showed that ablation of CD44 protected mice from HF diet-induced obesity, the CD44-deficient mice used in our study exhibited no changes in obesity or adiposity." (PMID 41301516, 2025). "We have previously shown that HA accumulation contributes to obesity-associated insulin resistance and that a reduction in HA or the genetic deletion of CD44 improves insulin resistance in obese mice." (PMID 41301516, 2025). "There is mounting evidence that ECM HA accumulation and increased CD44 expression are associated with obesity-related metabolic disorders, such as insulin resistance." (PMID 41301516, 2025). "pylori were examined, and modifying effect of FTO (the fat mass and obesity-associated protein) on CD44 was verified by MeRIP–qPCR." (PMID 36918410, 2023). "Herein, we narrow the focus to the roles of the collagen-integrin-ILK pathway and hyalurona-CD44 pathway as examples of processes involved in obesity-associated insulin resistance in adipose tissue." (PMID 37383542, 2023). "Specific deletion of ROCK1, a downstream kinase of the CD44/ankyrin/Cdc42 signaling pathway, attenuated obesity-associated insulin resistance in adipose tissue, indicating a role in obesity-related metabolic syndromes." (PMID 37894408, 2023). "In the present study, we focused on a specific factor associated with obesity and diabetes, CD44, and sought to refine our understanding of the relationship between CD44, obesity, and disease risk using genetic models in mice." (PMID 35410390, 2022). "One inflammatory protein associated with both obesity and the metabolic consequences of obesity is CD44, a cell-adhesion surface protein ubiquitously expressed and a primary ligand of hyaluronic acid." (PMID 35410390, 2022). "Previous studies in mice demonstrating the relationship between CD44 and obesity have been compelling and clearly demonstrated that CD44 deficiency reduces adiposity and improves insulin resistance." (PMID 35410390, 2022). "We investigated the relationship of CD44 with obesity in CD44-deficient mice challenged with a high-fat diet." (PMID 35410390, 2022). "Since obesity and insulin resistance are commonly associated with hepatic steatosis, hepatic TG content was measured in CD44-deficient mice." (PMID 35410390, 2022). "Obesity-associated T cell deficiencies extended beyond the tumor microenvironment, as evidenced by reduced proliferative capacity of CD44+CD8+ T cells in tumor-draining lymph nodes." (PMID 34064933, 2021). "Genetic deletion as well as antibody-mediated inhibition of CD44 ameliorated obesity-related metabolic disorders in association with reduced WAT inflammation and hepatosteatosis despite the similar body weight in mice fed with HFD." (PMID 34582891, 2021). "In this study, we examined the effect of CD44 deficiency on the development of diet-induced obesity and associated pathologies in mice." (PMID 23505504, 2013). "A similar correlation between CD44 expression and obesity was observed in WAT of WT mice and mice deficient in the nuclear receptor TAK1 (also called TR4) mice that are resistant to HFD-induced obesity." (PMID 23505504, 2013). "Importantly, modified brain CD44 levels were related to lipid metabolic benefits in lipid metabolic processes and insulin resistance, commonly associated with obesity, diabetes, and inflammatory disease." (PMID 40869172, 2025). "We can therefore suppose that the increased CD44 expression in the WAT might be another important link between obesity-induced inflammation and the higher risk of cancer." (PMID 39004641, 2024). "Cd44 antigen is a transmembrane protein expressed in both glial and neuronal cells, and its depletion has been linked to inflammation, neurite outgrowth, insulin resistance, and resistance to high-fat diet-induced obesity." (PMID 39329749, 2024).
Obesity (continued). "Nevertheless, our studies together with previous evidence suggest that CD44 may be a therapeutic target to treat obesity-associated metabolic diseases such as T2D." (PMID 38692289, 2024). "In the current study, we used two mouse models with different susceptibility to obesity and insulin resistance to determine a potential mechanism of action in which CD44 may contribute to the development of obesity." (PMID 35410390, 2022). "Thus, understanding in-vivo CD44 splice variant expression on T cell subsets during inflammatory processes such as obesity-mediated insulin resistance is an important area for further study." (PMID 21298111, 2011). "Therefore, targeting CD44 in (pre)adipocytes may provide therapeutic potential to treat obesity-associated metabolic complications." (PMID 38692289, 2024). "Thus, we had hypothesized that CD44-deficient mice with perturbed inflammatory response, such as C3H/HeJ mice, would fail to protect the mice from diet-induced obesity." (PMID 35410390, 2022). "In prior studies, we found that diet-induced obesity was associated with suppressed immune activity in the murine tumor microenvironment coincident with elevated frequencies of intra-tumoral Tregs expressing high levels of activation markers (CD44, ICOS) and suppressive mediators (PD-1, Lag3)." (PMID 36289552, 2022). "Studies have shown that increased CD44 expression is accompanied with obesity-induced hepatic steatosis and white adipose tissue-associated inflammation in human and mouse, suggesting CD44 might play a critical role in regulating obesity and associated pathologies." (PMID 25765115, 2015). "In both mice and humans with obesity, CD44 expression was elevated in VAT, particularly in regulatory T cells (Tregs) and inflammatory macrophages." (PMID 41077621, 2026). "In the left ventricle, eplerenone mitigated obesity‐induced elevations in SV, SW and CO, and caused an increase in EF, accompanied by elevated TGF‐β and RHAMM expression, and decreased CD44 expression." (PMID 41042601, 2026). "Hyaluronan (HA), a major ECM glycosaminoglycan, and its cell membrane receptors, CD44 and RHAMM (encoded by Hmmr), contribute to obesity-associated insulin resistance and cardio-renal dysfunction by promoting inflammation and fibrosis." (PMID 41002415, 2025). "By further functionalization using hyaluronic acid (HA) and MMP2 substrate‐linking P3 peptide‐modified HA (P3‐HA), an enhanced anti‐obesity effect is obtained by dual‐targeting of P3 and HA, and HA‐mediated CD44 poly‐clustering after MMP2 cleavage." (PMID 39324577, 2024). "An example of such a gene is Cd44, which is both upregulated in obesity, rescued by voluntary exercise, and downregulated by injection of miR-211." (PMID 39000297, 2024). "CD44 and RHAMM are main cell surface receptors of hyaluronan that have been implicated in metabolic regulation and obesity." (PMID 38908792, 2024). "CD44 was recently recognized as a major receptor for an extracellular matrix component that plays an essential role in promoting obesity and diabetes." (PMID 36936145, 2023). "Global deletion of CD44 in mice attenuates the development of obesity-induced adipose insulin resistance and glucose intolerance." (PMID 37383542, 2023). "In fact, CD44 has found to play a key role in non-alcoholic steatohepatitis development, a hepatic complication of MAFLD closely associated to the presence of obesity." (PMID 35896710, 2022). "Sex effects on obesity and fat distribution are well described in humans, and circulating CD44 was demonstrated to be higher in women than men." (PMID 35410390, 2022). "While C3H mice are more resistant to development of diet-induced obesity, CD44 deletion in C3H mice further increased lean mass and reduced fat mass to levels of pre-diet treatment." (PMID 35410390, 2022).
Obesity (continued). "OPN elicits its functions partly through its binding to the multifunctional membrane receptor CD44, for which circulating levels and expression in the AT increases in states of obesity and insulin resistance." (PMID 35406450, 2022). "We measured the effects of CD44 deficiency in both C57BL/6J and C3H/HeJ inbred mouse strains challenged with a high fat, high sucrose, obesity-inducing diet." (PMID 35410390, 2022). "Both C3H and B6 are protected from obesity when CD44 is inactivated, but results varied by mouse strain for liver fat and insulin sensitivity." (PMID 35410390, 2022). "Previous studies have shown that treating high-fat-diet mice with a monoclonal antibody of CD44 suppresses the development of obesity and reduces adipose tissue inflammation." (PMID 36613828, 2022). "Genes of interest include the mitochondrial citrate transporter Slc25a1, as well as genes known to regulate hematopoiesis (Cd44), anaerobic glycolysis (Ldha), and obesity/lipolysis (Plin1)." (PMID 32293246, 2020). "Recent literature reports have suggested the development of biased effector memory CD4 T cell differentiation characterized by increased CD44 under obesity-induced metabolic stress." (PMID 30134638, 2018). "It was found that CD44 knockout mice were protected against obesity and insulin resistance development." (PMID 29977307, 2018). "It is intriguing that the pro-inflammatory cytokine Opn, which interacts with CD44, has also been reported to play a role in cell migration, macrophage activation, and inflammation in obesity." (PMID 23505504, 2013). "CD44 expression is elevated in liver and white adipose tissue (WAT) during obesity suggesting a possible regulatory role for CD44 in metabolic syndrome." (PMID 23505504, 2013). "Our results showed increased expression of CD44 in VAT in obesity." (PMID 41077621, 2026). "Obesity-induced increases in HA deposition and CD44 and RHAMM expression are detrimental to the kidney via activation of the TGF-β1/Smad2/3, P38/JNK MAPK, and ROCK/ERK pathways, leading to glomerulopathy, tubular injury, inflammation, albuminuria, and elevated serum creatinine concentrations." (PMID 41301516, 2025). "Regardless, our triglyceride results suggest that RHAMM and CD44 may differentially regulate hepatic lipid metabolism in obesity." (PMID 41002415, 2025). "In line with this, our results showed that HF-diet feeding for 16 weeks increased renal CD44 protein expression, and the genetic deletion of CD44 in mice ameliorated obesity-induced tubular injury and renal dysfunction, providing evidence for a crucial role of CD44 in ORKP." (PMID 41301516, 2025). "Our results suggest a working model where obesity induces renal HA accumulation and CD44 and RHAMM expression, which activates the TGF-β1/Smad2/3, P38/JNK MAPK, and ROCK2/ERK/Akt pathways, promoting transcription of profibrotic and proinflammatory genes and contributing to the development of ORKP." (PMID 41301516, 2025). "As a candidate gene for the development of obesity and diabetes, CD44 may be a key mediator of the systemic inflammation response associated with obesity and diabetes, participating in the regulation of inflammatory responses." (PMID 40309438, 2025). "Ablation of CD44 ameliorates adipose tissue inflammation and insulin resistance in obesity." (PMID 38692289, 2024). "However, recent studies suggest a potential role of CD44 in chronic metabolic diseases, such as obesity and T2D." (PMID 38692289, 2024). "Moreover, CD44, one of the main cell surface receptors for the ECM hyaluronan, is implicated in obesity and Type 2 diabetes, as genetic ablation of CD44 or its pharmacological inhibition improves diet-induced disruptions of glucose homeostasis in mice." (PMID 37383542, 2023). "Interestingly, in a high fat diet mouse model, CD44 blockade with a neutralizing antibody prevented obesity, reduced insulin resistance, and ameliorated adipose tissue inflammation." (PMID 37805649, 2023).